TCF3 (transcription factor 3)
Description:
Transcriptional regulator involved in the initiation of neuronal differentiation and mesenchymal to epithelial transition (By similarity). Heterodimers between TCF3 and tissue-specific basic helix-loop-helix (bHLH) proteins play major roles in determining tissue-specific cell fate during embryogenesis, like muscle or early B-cell differentiation (By similarity). Together with TCF15, required for the mesenchymal to epithelial transition (By similarity). Dimers bind DNA on E-box motifs: 5'-CANNTG-3' (By similarity). Binds to the kappa-E2 site in the kappa immunoglobulin gene enhancer. Binds to IEB1 and IEB2, which are short DNA sequences in the insulin gene transcription control region (By similarity). [Isoform E47]: Facilitates ATOH7 binding to DNA at the consensus sequence 5'-CAGGTG-3', and positively regulates transcriptional activity.
Synonyms: bHLHb21; TCF-3; E2A; ITF1; MGC129647; MGC129648; VDIR; E47; p75; AGM8; AGM8A; AGM8B
Tractability: PROTAC: UniProt records ubiquitination sites on it; ubiquitination databases record sites on it; its protein half-life has been measured.
Gene: Protein-coding gene on chromosome 19 (1,609,291 to 1,652,911, reverse strand). Ensembl gene ENSG00000071564.
Subcellular location: Nucleus
Subcellular location (Human Protein Atlas): Nucleoplasm
Pathways (Reactome):
Cell-Cell communication: Negative Regulation of CDH1 Gene Transcription
Chromatin organization: CHD1 and CHD2 subfamily
Developmental Biology: Myogenesis
Gene expression (Transcription): RUNX1 regulates transcription of genes involved in differentiation of HSCs
Signal Transduction: TGFBR3 expression
Gene Ontology:
Molecular function: bHLH transcription factor binding; DNA binding; DNA-binding transcription activator activity, RNA polymerase II-specific; DNA-binding transcription factor activity; DNA-binding transcription factor binding; DNA-binding transcription repressor activity, RNA polymerase II-specific; E-box binding; mitogen-activated protein kinase kinase kinase binding; protein binding; protein heterodimerization activity; protein homodimerization activity; RNA polymerase II cis-regulatory region sequence-specific DNA binding; RNA polymerase II-specific DNA-binding transcription factor binding; vitamin D response element binding; cis-regulatory region sequence-specific DNA binding; DNA-binding transcription factor activity, RNA polymerase II-specific; protein dimerization activity
Biological process: immunoglobulin V(D)J recombination; negative regulation of transcription by RNA polymerase II; positive regulation of DNA-templated transcription; positive regulation of transcription by RNA polymerase II; B cell differentiation; B cell lineage commitment; positive regulation of neuron differentiation; regulation of DNA-templated transcription; regulation of transcription by RNA polymerase II
Cellular component: chromatin; cytoplasm; euchromatin; nucleoplasm; nucleus; RNA polymerase II transcription regulator complex; transcription regulator complex
Genetic constraint (gnomAD): Loss-of-function variants: 55 observed, 55.57 expected, observed/expected ratio (o/e) 0.99, 90% interval 0.8 to 1.24. The synonymous counts are far from expectation, so gnomAD's model fits this gene poorly and the ratio says little. Missense variants: 1,078 observed, 811.8 expected, observed/expected ratio (o/e) 1.33, 90% interval 1.26 to 1.4. Synonymous variants: 525 observed, 361.85 expected, observed/expected ratio (o/e) 1.45, 90% interval 1.35 to 1.56.
Gene-disease validity (ClinGen):
ClinGen rates the evidence that TCF3 causes each of these diseases.
autosomal agammaglobulinemia (semidominant): Definitive. Agammaglobulinemia, non-Bruton type (autosomal agammaglobulinemia) is a rare form of agammaglobulinemia, a primary immunodeficiency disease, and is characterized by variable immune dysfunction with frequent and recurrent bacterial infections and/or chronic diarrhea.
Homologues: Orthologues: macaque TCF3 (98% identical), chimpanzee TCF3 (93% identical), mouse Tcf3 (83% identical), rat Tcf3 (82% identical), guinea pig TCF3 (82% identical), dog TCF3 (80% identical), pig TCF3 (80% identical), tropical clawed frog tcf3 (63% identical), zebrafish tcf3b (56% identical), zebrafish tcf3a (45% identical), Drosophila melanogaster da (28% identical), Caenorhabditis elegans hlh-2 (15% identical). Paralogues in human: TCF12 (54% identical), TCF4 (53% identical).
Diseases named in the same sentence as TCF3 in open-access papers:
TCF3 is named in the same sentence as 173 diseases in open-access papers, as found by Europe PMC text mining. Sharing a sentence is not in itself a finding about the gene and the disease. The quoted sentences say what the papers report.
leukemia (35 papers, 2005 to 2026). A malignant (clonal) hematologic disorder, involving hematopoietic stem cells and characterized by the presence of primitive or atypical myeloid or lymphoid cells in the bone marrow and the blood. "TCF3::PBX1 + mouse leukemias show consistent loss of tumor-suppressor genes (PAX5 and CDKN2A/2B) and activation of signaling pathways by point mutations (JAK/STAT, RAS/MAPK)." (PMID 35269896, 2022). "Notably, we also established a B-ALL cell line from the GR-BALL-3 sample, validated at the phenotypic and genomic levels, in which expression of the TCF3::HLF fusion transcript associated with aggressive leukemia has been confirmed." (PMID 37723198, 2023). "Our study provides insight into how TCF3::HLF rewires the 3D genome to drive leukemia and serves as a resource for further exploration of the TCF3::HLF regulome." (PMID 42090509, 2026). "In a syngeneic murine model of TCF3::PBX1 leukemia, an upregulation of PD-1, TIM-3, and LAG3 on CD4+ and CD8+ T cells was observed in the presence of leukemia." (PMID 40503229, 2025). "We present a unique case of an adult with mixed lineage leukemia with TCF3::ZNF384 fusion presenting as an indolent isolated mediastinal mass." (PMID 39531055, 2025). "This is the first presentation of leukemia with TCF3::ZNF384 fusion as an isolated mediastinal tumor." (PMID 39531055, 2025). "We report the first case of TCF3::ZNF384 mixed-phenotype leukemia presenting as isolated extramedullary disease in the mediastinum." (PMID 39531055, 2025). "TCF3-HLF fusions hijack endogenous stem cell functions to drive leukemia by activating SE, which are generally active in hematopoietic stem and progenitor cells (HSPCs)." (PMID 39090713, 2024). "TCF3::HLF leukemia is a rare subtype of B-cell acute lymphoblastic leukemia (B-ALL) with extremely poor prognosis, which accounts for less than 1% of childhood B-ALL." (PMID 35269896, 2022). "SuperDendrix also finds associations for three downstream targets of TCF3 and IRF4 transcription factors: BCL2 and {leukemia, myeloma, MEF2B(A)}, PIM2 and myeloma, and POU2AF1 and Myeloma,MEF2BA." (PMID 35382456, 2022). "TFPT (FB1), the nearest one adjacent to PRPF31, is reported to be related to development of leukemia, acting as a molecular fusion partner of TCF3 (E2A)." (PMID 36431159, 2022). "Despite its clinical significance, the mechanisms by which TCF3::HLF induces leukemia are unclear." (PMID 42090509, 2026). "TCF3::HLF expression induces transcriptional alterations in pre-leukemia cells." (PMID 35269896, 2022). "MMD-HSCTs are reserved for a PCR-MRD TP2 ≥5 × 10−3, all TCF3-HLF fused leukemias and those with IF." (PMID 35004545, 2021). "Somatic fusion genes of these genes such as NUP98-HOXD11 and TCF3-HLF were found in leukemia." (PMID 27701467, 2016). "Specifically, in the poor prognosis B-ALL type harboring the TCF3-HLF translocation, ERG cooperates with TCF3-HLF to regulate enhancer functions and is essential for leukemia maintenance." (PMID 37735473, 2023). "Some of these cryptic gene fusions, including NUP98-NSD1, P2RY8-CRLF2 and TCF3-HLF, are recurrently seen in pediatric leukemias and their prognostic significance has been demonstrated." (PMID 32131829, 2020). "Leukemia derived from this developmental stage usually displays TCF3/PBX1 chromosomal rearrangement, which is commonly found in leukemia derived from pre-B lymphocytes (in more than 90% of cases)." (PMID 32102485, 2020). "A previous study by Fernando and colleagues also evaluated lncRNA expression signatures in genetic subtypes of human BCP-ALL using 14 ETV6/RUNX1, 15 TCF3/PBX1 and 15 MLL-rearranged leukemia specimens." (PMID 27650541, 2016). "This included two leukemia cell lines, RCH-ACV and REH, known to carry the TCF3:PBX1 and ETV6:RUNX1 fusion genes, respectively, and four prostate cancer samples positive for the TMPRSS2:ERG fusion gene." (PMID 19152679, 2009).
leukemia (continued). "Using this array, proof of principle was demonstrated by detection of known fusion genes (such as TCF3:PBX1, ETV6:RUNX1, and TMPRSS2:ERG) from all six positive controls consisting of leukemia cell lines and prostate cancer biopsies." (PMID 19152679, 2009). "Notably, TCF3::HLF directly regulates MEF2C expression through its enhancer, as interference disrupted MEF2C transcription and inhibited leukemia propagation." (PMID 42090509, 2026). "Moreover, SE activity of TCF3-HLF is mediated through the recruitment of EP300; thus, BRD4 inhibitor JQ1 and EP300 inhibitor A-485 are two reasonable options for TCF3-HLF-fusion leukemia." (PMID 39090713, 2024). "However, ETV6::RUNX1, TCF3::PBX1, and T‐ALL had low MTXPG intracellular accumulation in leukemia cells." (PMID 39485718, 2024). "Although the generation of Tcf3-Hlf was not sufficient to induce leukemia in this study the model can now be used to evaluate different cells of origin and to screen for required cooperative genetic events." (PMID 33134860, 2020). "On the other hand, TCF3, also named transcription factor E2-alpha (E2A), is a multifunctional BHLH (basic helix loop helix) transcription factor and plays a crucial role in the development and differentiation of lymphocytes, being correlated with the development of lymphoma and leukemia." (PMID 38893499, 2024). "Surprisingly, the restoration of miR-24 expression in TCF3-rearranged leukemic cell lines neither affects the expression of some of its targets nor alters the frequency of apoptotic cells, suggesting that MYC is regulated by a combination of mechanisms in this type of leukemia." (PMID 32102485, 2020).
acute lymphoblastic leukemia (34 papers, 2008 to 2026). Leukemia with an acute onset, characterized by the presence of lymphoblasts in the bone marrow and the peripheral blood. "EP300 promotes acute lymphoblastic leukemia by regulating TCF3 HLF (American Association for Cancer Research, 2020)." (PMID 34149798, 2021). "Acute leukemia with TCF3::ZNF384 is a distinct type of acute leukemia that present most commonly as B-acute lymphoblastic leukemia or mixed-phenotype acute leukemia (B/myeloid)." (PMID 39531055, 2025). "An example of this is the TCF3-HLF chimeric transcription factor (TF) seen in juvenile acute lymphoblastic leukemia (ALL)." (PMID 39838405, 2025). "In contrast, the dependency on TCF3 in acute lymphoblastic leukemia and non-Hodgkin lymphoma was considerably weaker." (PMID 37554444, 2023). "The present case report features a highly uncommon form of a paediatric TCF3-HLF positive acute lymphoblastic leukaemia (ALL) relapse, an extramedullary, peripheral bone manifestation." (PMID 36553362, 2022). "For instance, HtrA3 is downregulated in B-cell and T-cell acute lymphoblastic leukemia and acute myeloid leukemia, yet HtrA3 is significantly increased in acute lymphoblastic leukemia where chromosome translocation has occurred at 11q23/MLL or TCF3/PBX1." (PMID 34639128, 2021). "A novel HL susceptibility locus on chromosome 19p13.3 has been recently identified and includes the transcription factor 3 gene (known as TCF3 or E2A immunoglobulin enhancer-binding factors E12/E47), previously known to be associated with pre-B-cell acute lymphoblastic leukemia (B-ALL)." (PMID 29587466, 2018). "Of these, TCF3 translocation junctions were seen to cluster at or near transposable elements in a majority of TCF3-PBX1 acute lymphoblastic leukemia." (PMID 24135088, 2013). "Two of the high-scoring translocations included 19p13, the site of the TCF3 gene, which is frequently found translocated in acute lymphoblastic leukemia." (PMID 23028501, 2012). "However, in B-cell progenitor acute lymphoid leukemia (BCP-ALL) PBX1 is part of the fusion gene TCF3::PBX1, and in Hodgkin lymphoma PBX1 is aberrantly activated, demonstrating that deregulated PBX1 acts as an oncogene in B-cell malignancies." (PMID 39689089, 2024). "HLF, which is high-expressed in liver tissues but low-expressed lung tissues, is initially identified as a protein related to TCF3 driving acute lymphoblastic leukemia, but it is also demonstrated to be robustly hypermethylated in NSCLC when compared to normal tissues." (PMID 33612479, 2021). "T cytokine 3 (TCF3, also known as E2A) is closely related to human acute lymphoid leukemia." (PMID 32799626, 2020). "The identity of the specific gene on 19p13 that is associated with DLBCL is not yet known; however, TCF3 has been reported to be associated with acute lymphoblastic leukemia, and microRNA (miRNA) genes have been implicated in mature B-cell neoplasia." (PMID 24220305, 2013). "Another study focuses on the dysregulation of MT1 metallothionein subtypes in TCF3::PBX1 pre-B-cell acute lymphoblastic leukemia (ALL)." (PMID 40806565, 2025).
breast carcinoma (31 papers, 2009 to 2025). "The increased expression of TCF3 could enhance the proliferation, invasion, and metastasis of breast cancer cells and was associated with poor prognosis." (PMID 38893499, 2024). "Association of TCF3 and Id family factors with the basal sub-type of breast cancers and their lower expression in luminal types may imply a down-regulation by ER and/or PR, but this has not been specifically reported." (PMID 26797644, 2016). "Furthermore, the analysis of TCF3 expression in several breast carcinomas dataset showed that TCF3 upregulation associated to the basal-like phenotype (upper) and exemplified in dedifferentiated breast carcinoma MDA-MB435 cells." (PMID 23555842, 2013). "TCF3 silencing has been shown to impair the self-renewal capacity of breast cancer cells and reduce the expression of stemness-related genes." (PMID 41153808, 2025). "Regarding the biomarker potential in breast cancer, our resultssuggest that LEF1, TCF3, TCF4, and specially TCF7, have significant diagnostic valueto distinguish breast cancer patients from healthy individuals and a role insubtyping insight." (PMID 38100720, 2023). "In the current study, we revealed a feedback loop formed by miR-182-5p/CMTM7/CTNNA1/CTNNB1/TCF3 in breast cancer progression." (PMID 36829181, 2023). "We identified a feedback loop with the composition of miR-182-5p, CMTM7, CTNNA1, CTNNB1 (β-catenin), and TCF3, which play essential roles in breast cancer progression." (PMID 36829181, 2023). "The overexpression of TCF3 has been detected in several types of human cancers, including Wilms’ tumor, breast cancer, renal carcinoma and embryonal carcinoma." (PMID 36231068, 2022). "At the same time, studies have found that silencing the expression of TCF3 can greatly reduce the possibility of forming the tumor of breast cancer, leading to a decrease in tumor growth rate." (PMID 34658308, 2021). "This study was designed to research the influence of activating transcription factor 3 (ATF3) on the radioresistance of breast cancer." (PMID 30117642, 2018). "E47 (also known was TCF3) is a repressor of E-cadherin and its activity has been implicated in epithelial-mesenchymal transition events in breast cancer." (PMID 25996148, 2015). "Tumours were sub-classified into two main clusters, indicating that TCF3 (E47/E12) and ID genes are differentially expressed among breast carcinomas." (PMID 23555842, 2013). "In breast cancer, TCF3 is involved in the regulation of breast cancer cell differentiation state and tumorigenicity." (PMID 23940558, 2013). "Also, breast cancer cells treated with GSK591 showed decreased TCF3 exon 18A/18B ratio under hypoxia which indicated that PRMT5-mediated symmetric dimethylation is important for regulation of TCF3 alternative splicing event." (PMID 41150697, 2025). "Elevated TCF3 expression in human gliomas or poorly differentiated breast cancers may drive tumor progression via activation of the Akt/Erk signaling pathways, initiating tumor proliferation." (PMID 39205642, 2024). "In summary, our study uncovered the existence of the miR-182-5p/CMTM7/CTNNA1/CTNNB1/TCF3 regulation loop in breast cancer, which may provide novel targets and promising strategies for breast cancer therapy." (PMID 36829181, 2023). "A feedback loop formed by miR-182-5p/CMTM7/CTNNA1/CTNNB1/TCF3 may play a critical role in breast cancer." (PMID 36829181, 2023). "TCF3 protein was initially reported to play particularly important roles during lymphocyte development, and it is dysregulated in various cancers including lymphoma, pancreatic cancer, breast cancer, colorectal cancer, and prostate cancer." (PMID 34175897, 2021).
breast carcinoma (continued). "Breast cancer growth and initiation were controlled by TCF3." (PMID 28953220, 2017). "Similarly, the next ranked regulator TCF3 has been found to regulate breast cancer cell differentiation and tumorigenicity." (PMID 27818995, 2016). "Additionally, TCF3 is supposed to be involved in breast cancer growth and initiation and is preferentially highly expressed in breast cancer with poor prognosis of the basal-like subtype." (PMID 26627005, 2015). "Knockdown of fascin (fascin−) in basal-like triple-negative MDA-MB-231 breast cancer cells, which are naturally fascin positive (fascin+), significantly (p < 0.05) reduced the protein expression of β-catenin, as well as TCF3 and cyclin D1, known β-catenin targets." (PMID 32373510, 2020). "This study shows that PRMT5 regulates TCF3 alternative splicing under hypoxia and that this promotes EMT and invasion of breast cancer cells." (PMID 41150697, 2025). "Collectively, our results indicate PRMT5-mediated symmetric arginine dimethylation of histones regulates alternative splicing of TCF3 gene thereby enhancing EMT and invasion in breast cancer hypoxia." (PMID 41150697, 2025). "Further to check the effect of E47 isoform on the invasion of breast cancer cells, we overexpressed FLAG-tagged TCF3-18A (E12) and TCF3-18B (E47) isoforms and performed Matrigel invasion assay in both MCF7 and MDA-MB231 cell lines." (PMID 41150697, 2025). "PTBP1 promotes the exclusion of exon 18a which results in the production of the pro-invasive TCF3-18B (E47) isoform which promotes EMT and invasion of breast cancer cells under hypoxia." (PMID 41150697, 2025). "In summary, we suggest that LEF1, TCF3,TCF4, and TCF7 have the potential to bebiomarkers in breast cancer clinics." (PMID 38100720, 2023). "TCF3, another bHLH transcription factor, is able to induce EMT in breast cancer cells by directly suppressing E-cadherin through binding to E-boxes of the promoter called E-pal and E3." (PMID 26797644, 2016). "As for TCF3, while there is no study on its role in endocrine resistance, it is important for breast cancer differentiation, development, and prognosis." (PMID 35401937, 2022). "Additionally, in the MDA-MB-435 breast cancer cell line the presence of wild-type or mutant E-cadherin proteins leads to the differential regulation of a variety of EMT inducers (Snail, Twist, ZEB1, TCF3)." (PMID 19257890, 2009). "Firstly, to understand TCF3 splicing pattern and its dependency on PRMT5 in breast cancer hypoxia, we performed qRT-PCR analysis with or without GSK591 treatment using primers designed specifically against exons 18A and 18B." (PMID 41150697, 2025).